EGFR (epidermal growth factor receptor)
Diseases named in the same sentence as EGFR in open-access papers (continued):
Sharing a sentence is not in itself a finding about the gene and the disease.
cancer (continued). "Although EGFR is an enriched dependency in HNSCC and EGFR inhibitors are most active in killing HNSCC relative to other cancers, Cetuximab is the only approved targeted therapy for use in HNSCC." (PMID 34907286, 2021). "While non-genetic resistance mechanisms, including transcriptional reprogramming, are increasingly being recognized in several cancer types, they are currently largely ignored in the context of anti-EGFR SR in CRC." (PMID 34271981, 2021). "IL13Rα2 was described to be upregulated following activation of EGFR and mutant EGFRvIII in cancer cells." (PMID 33917458, 2021). "As the result, the loss of E-cadherin often observed in cancer cells leads to activation of EGFR signalling, thus, promoting cancer cell dissemination." (PMID 35127732, 2021). "Herein, we describe the clinical course of an older adult patient with PON whose loss of vision improved after switching between epidermal growth factor receptor-tyrosine kinase inhibitor (EGFR-TKI) treatments for cancer." (PMID 34327032, 2021). "Epidermal growth factor receptor (EGFR) is a protein-based receptor that also assists cancer cell growth." (PMID 34440099, 2021). "The lessons from development of EGFR inhibitors highlight the importance of predictive biomarkers in guiding precision cancer therapy." (PMID 34419139, 2021). "In cancer cells, binding the ligand to the EGFR also leads to its dimerization and transduction of the signal to the cell interior." (PMID 33435596, 2021). "Further, the study showed that there were differences in the staging of cancer between the two groups with EGFR mutant cancer being more likely to be diagnosed at a more advanced stage." (PMID 34055528, 2021). "Fourteen EGFR small-molecule inhibitors have been approved so far for the treatment of different types of cancers." (PMID 34771085, 2021). "The human epidermal growth factor receptor (HER-2) protein is involved in cancer cell proliferation, differentiation, and apoptosis." (PMID 34638601, 2021). "It was shown that the EGFR-specific Affibody molecule was bound to and taken up by EGFR-expressing A431 cancer cells." (PMID 34769444, 2021). "Elevated levels of EGFR enable signal transduction in the cell cytoplasm, thereby promoting tumorigenesis by contributing to the transformation of cellular phenotypes for cancer cell proliferation and survival." (PMID 34576006, 2021). "We investigated the protein expression of ANXA6 and EGFR in cancer tissue from 81 patients with TNBC." (PMID 34238922, 2021). "70% of patients had coamplifications of receptor tyrosine kinase or other cancer-promoting genes, including MET, KRAS, FGFR1, IGFR1, SRC and VEGFA18–20, potentially associated with resistance to EGFR-inhibitors." (PMID 33199443, 2021). "The activated EREG/EGFR pathway regulates various cellular functions, including cancer cell proliferation, survival, metastasis, and angiogenesis, thereby conferring malignant tumor phenotypes." (PMID 34884633, 2021). "Overall, these results suggest an involvement of the EGFR signaling in mediating vp17s clonogenicity through the modulation of several molecules involved in cancer progression." (PMID 33093643, 2021). "From a biological point of view, TA is particularly promising in those cancer types that overexpress the epidermal growth factor receptor (EGFR), as TA regulates its activation and downstream signaling pathways, eliciting the apoptosis process." (PMID 33499388, 2021). "The OS in both the groups were comparable with EGFR mutant cancer patients having a median survival of ~49 months and those with other mutations surviving ~53 months." (PMID 34055528, 2021).
cancer (continued). "Owing to EGFR mediation of cell proliferation, migration, and angiogenesis via intracellular signaling that is often dysregulated in cancer, this protein is a potential target for cancer therapeutics." (PMID 32400038, 2021). "Conjugation of EVs with either an epidermal growth factor receptor (EGFR)‐targeting peptide or anti‐EGFR nanobody facilitates their accumulation in EGFR‐positive cancer cells, both in vitro and in vivo." (PMID 33643546, 2021). "On the contrary, copper chelators can inhibit STAT3 and EGFR phosphorylation in cancer cells, to enhance PD-L1 degradation in vitro and in vivo, leading to strong anti-tumor activities." (PMID 34639141, 2021). "The dynamics of EGFR activity and possible crosstalk between several possible PTMs, including other phosphorylation sites, on HDAC1 warrant further study to characterize the intricacies of HDAC1 regulation in EGFR-driven cancers." (PMID 33976119, 2021). "The RTK, epidermal growth factor receptor (EGFR), and glycolytic protein hexokinase-2 (HK2) influence cell growth and the overexpression of both have been linked to more invasive and aggressive cancers." (PMID 34748597, 2021). "We also identified further cancer-related pathways, namely, choline metabolism in cancer, central carbon metabolism in cancer, and EGFR tyrosine kinase inhibitor resistance." (PMID 34824199, 2021). "This highlights the importance of understanding the regulation and function of the EGFR signalling for novel cancer therapies." (PMID 35127732, 2021). "Unlike mAbs or TKIs, which kill cancer cells only by inhibiting EGFR signaling, EGFR-targeting ADCs work mainly by binding to antigens on cancer cells, internalization into lysosomes and then releasing payloads to kill the cells." (PMID 34879870, 2021). "Elevated levels of EGFR were observed in various human cancers, which enabled the signal transduction in cell cytoplasm and thereby promote tumorigenesis." (PMID 33925065, 2021). "In EGFR-mutated NSCLC, inhibition of the Shh pathway sensitizes primary tissues and cancer cell lines both to classic chemotherapy and EGFR-TKIs, suggesting a role for Hh pathway in resistance to EGFR TKI." (PMID 34970481, 2021). "AREG is a ligand of epidermal growth factor receptor (EGFR), which is aberrantly expressed and plays a vital role in numerous types of cancer by mediating the motility, metastasis, and proliferation of cancer cells." (PMID 34143198, 2021). "HT-29 and HCT-116 cells also differ in their EGFR expression, which is involved in cancer cells migration and invasion capabilities." (PMID 33671096, 2021). "Given that approximately 50% of all cancer deaths is attributable to the EGFR-overexpressing human epithelial cancers, this led us to synthesize the 188Re-liposome-Fcy-hEGF/5-FC with radio- and chemo-toxicity." (PMID 33672989, 2021). "We previously showed that suppression of PGRMC1 through knockdown significantly enhanced the cytotoxicity of cancer cells by anti-cancer agents, including the EGFR inhibitor erlotinib." (PMID 34209885, 2021). "Approximately, 30% of all cancer subtypes fall into the category CMS2 (elevated EGFR levels) or CMS4 (mesenchymal-like)." (PMID 33570712, 2021). "Well-known biological markers of cell proliferation, including MCM-2 and Ki-67, along with the proto-oncogene, EGFR, have been reported to play pivotal roles in the pathogenesis of several cancers, including LSCC2,3." (PMID 34272446, 2021). "Excitation of the EGF/EGFR signaling pathway promotes the proliferation and invasion of cancer cells." (PMID 33980265, 2021).
cancer (continued). "Paclitaxel induces apoptosis and inhibits cancer cell proliferation through different signal transduction pathways including, the epidermal growth factor receptor pathway (EGFR)." (PMID 34180747, 2021). "EGFR is overexpressed in a number of cancers, particularly in tissue of epithelial origin, including glioma, head and neck, lung, breast, renal, bladder, and prostate cancer." (PMID 33711962, 2021). "This leads to the transmission of excessive pro-survival and pro-proliferation signals, which in turn lead to cancer initiation and progression; the efficacy of EGFR-TKIs lies in lowering these excessive pro-survival and pro-proliferation signals." (PMID 34831415, 2021). "The EGFR inhibitors can also be classified into three groups based on the types of cancers for which they are approved." (PMID 34771085, 2021). "To assess the role of the stromal compartment in altering cancer cells’ response to treatment, we used the EGFR tyrosine kinase inhibitor PD153035." (PMID 34885111, 2021). "LR004-VC-MMAE showed effective antitumor activity by inhibiting the activation of EGFR signaling and the expression of cancer stemness marker genes." (PMID 34879870, 2021). "We propose a new therapeutic option for NSCLC with acquired EGFR-TKI resistance that focuses on cancer metabolism." (PMID 34367462, 2021). "LR004-VC-MMAE also inhibited the activation of EGFR signaling and the expression of cancer stemness marker genes such as Oct4, Sox2, KLF4 and EpCAM." (PMID 34879870, 2021). "The KRAS gene is an essential biomarker in cancer, mainly because it predicts the efficacy in therapies targeting the growth factor EGFR in tumors such as colorectal cancer." (PMID 34663841, 2021). "Active ligands were functionalized on fluorescent gold nanoparticles to highlight the endocytosis process in different cancer cell lines with variable EGFR expressions." (PMID 34163672, 2021). "Epidermal growth factor receptor (EGFR) specific therapeutics is of great importance in cancer treatment." (PMID 33672989, 2021). "Similar observations were noticed in osimertinib resistant primary cancer cells in both EGFR-dependent and independent manner." (PMID 33740988, 2021). "In detail, EGFR, in multiple cancer settings, stimulated the phosphorylation of unliganded EphA2 via AKT and p90RSK at S897." (PMID 33572284, 2021). "Based on this, the AnxA1/EGFR interaction seems to play a relevant role in immune suppression in the cancer context." (PMID 34571894, 2021). "Reciprocal cross talk between the STAT3 and EGFR pathways is a key molecular mechanism leading to resistance in cancer cells." (PMID 33259114, 2021). "Our data indicate that 1,2-NQ induces activation of the EGFR–Akt signaling pathway via binding directly to EGFR and that this modification renders cancer cells resistant to apoptotic stimuli." (PMID 33705793, 2021). "ATTACK (Asymmetric Tandem Trimerbody for T cell Activation and Cancer Killing) is a single-chain anti-EGFR T-BsAb with trivalent EGFR binding and monovalent CD3 binding." (PMID 34832954, 2021). "EGF activates the mitochondrial translocation of EGFR, mitochondrial fission, and redistribution, upregulates cellular ATP production, and enhances cancer cell motility in vitro and in vivo." (PMID 33498743, 2021). "Because HAF stably maintains the capsid form, HAF is a suitable nanoparticle for stably targeting and treating cancers that overexpress EGFR." (PMID 34502049, 2021). "By labeling with a heterodimeric peptide ligand, the gold nanoparticles specifically target overexpression of EGFR and ErbB2 by the cancer cells." (PMID 34832857, 2021). "A poor prognosis in those with certain cancers such as cervical, bladder, head and neck, and ovarian cancers, has been found to have an important correlation with EGFR overexpression." (PMID 33980265, 2021).
cancer (continued). "A similar dynamic of receptor post-translational modification also occurs during activation of the epidermal growth factor receptor (EGFR) in human tumorigenesis and cancer progression." (PMID 33980819, 2021). "The mitogen-activated protein kinase (MAPK) pathway incorporates kinases, e.g., MEK and ERK, to modulate cancer via EGFR signaling." (PMID 34067095, 2021). "Evidence of pre-existing mutations is consistent with a direct oncogenic role and in vitro demonstrations of enhanced EGFR phosphorylation and cancer-cell survival." (PMID 34069119, 2021). "The lipid portion of SA-5 is in the lipid bilayer of the liposome whereas the peptide part is exposed on the surface of liposome providing the targeting effect to bind to EGFR dimers on cancer cells." (PMID 33800723, 2021). "Currently, several EGFR inhibitors have been used in the treatment of cancers, such as tyrosine kinase inhibitors (TKI) (eg erlotinib and gefitinib) and monoclonal antibodies (eg cetuximab and necitumumab)." (PMID 33960631, 2021). "Epidermal growth factor receptor (EGFR) has been widely studied and known to overexpress in various types of cancers." (PMID 34582442, 2021). "EGFR signaling regulates cell proliferation and survival, and the overactivation of the receptor promotes cancer development." (PMID 33633298, 2021). "While PLK1 inhibition has been well established to sensitize the cancer cells to radiation via mitotic regulation, EGFR is reported to be an arbitrator of DNA repair and is upregulated in ~ 50% of pulmonary carcinoma patients." (PMID 34138386, 2021). "Overexpression of EGFR is known to drive a subset of aggressive cancers, including squamous cell head and neck, glioma, non-small cell lung, colorectal, ovarian, breast and cervical cancers." (PMID 33535661, 2021). "Supporting previous findings that super-enhancers play important roles in cell identity and cancer hallmarks, we observed super-enhancers associated with several known GC oncogenes, such as MYC, KLF5, and EGFR." (PMID 34635154, 2021). "Receptor tyrosine kinase (RTK) such as epidermal growth factor (EGFR) plays an important role in determining survival and progression of cancer cells." (PMID 34829591, 2021). "Honokiol (HNK) is a potent anti-tumor agent that affects EGFR and mitochondrial function to inhibit the cancer cells’ genesis and metastasis." (PMID 33498743, 2021). "Dicentrine, another aporphine alkaloid, has been shown to exert cytotoxic activity towards cancer cells by binding to EGFR." (PMID 34237060, 2021). "Beside this, Huang and collaborators also described that FPR1 signaling pathway is responsible for the transactivation of the epidermal growth factor receptor (EGFR) that would result in cancer progression." (PMID 34571894, 2021). "The strategy of targeting EGFR proved highly successful for treating a range of cancers and the identification of new scaffold with interesting activity is important in the development of new therapies to overcome disease resistance." (PMID 33639651, 2021). "Epidermal growth factor receptor (EGFR) is an oncogenic transmembrane receptor that is overexpressed in many cancers, including GC." (PMID 34966746, 2021). "Nanotargeted 188Re-DXR-IL-C225 has been studied the cytotoxic effects for EGFR positive cancer cells in vitro." (PMID 33672989, 2021). "Given EGFR’s frequent alteration in cSCC and its critical roles in cancer progression, EGFR represents an attractive therapeutic target with both antibodies and small molecule inhibitors being developed." (PMID 34553848, 2021). "SGLT1 and epidermal growth factor receptor (EGFR, an oncoprotein) interaction can promote protein stability and activity each other in cancer cells." (PMID 34439414, 2021). "Neuropipin-2 (NRP2), a non-tyrosine kinase receptor frequently overexpressed in various malignancies, including GBM, regulates endosome maturation and EGFR trafficking, supporting the growth and replication of cancer cells." (PMID 34021236, 2021).
cancer (continued). "EGFR overexpression is generally found in many types of human cancer and is currently used in multiple cancer treatment targets in clinical practice." (PMID 33980265, 2021). "The second antigen-binding domain binds another target, e.g., other antigen associated with cancer (CD19, CD38, HER2, EGFR, CEA, or IL-13R-a2), or a cancer-related ligand (IL-13, heregulin, VEGF)." (PMID 33482842, 2021). "Our study proposes novel and safe drug-loaded targeted nanosystems for EGFR-positive TNBC with excellent potential for the application in cancer diagnosis and therapy." (PMID 34294133, 2021). "Cetuximab, a humanized monoclonal antibody against epidermal growth factor receptor (EGFR), has been linked to IR700 resulting in the generation of a conjugate that showed high selectivity and efficacy against various cancer types both in vitro and in vivo." (PMID 34283089, 2021). "In cancer cells with high levels of Gene 33 expression, Gene 33 knockdown promotes cell proliferation by increasing EGFR signaling, whereas in cells with low EGFR expression, Gene 33 depletion inhibits cell proliferation by enhancing AKT dephosphorylation." (PMID 34206547, 2021). "Previous results showed that only 10–20% of cancer patients have major clinical responses to EGFR inhibition, either because they barely respond primarily or they acquire resistance during anti-EGFR treatment." (PMID 34257586, 2021). "Cancer cell resistance to chemotherapy and radiotherapy through EGFR overexpression negatively affects therapeutic success." (PMID 34094980, 2021). "Another reporting evidence shows that BPA induces cancer cell proliferation via activation of EGFR activity." (PMID 34311656, 2021). "The same was observed for the second EGFR-positive cancer cell line CAL-27 with a significantly higher (p < 0.0001) number of AuNRs aggregates per cell in the targeted than in the untargeted AuNRs." (PMID 34683944, 2021). "HER3 also contributes to drug resistance via upregulation of HER3 in cancer cells resistant to EGFR-TKIs." (PMID 33801379, 2021). "The 3-(1-hydroxy-1-phenylpropan-2-yl)-2-(methylthio)quinazolin-4(3H)-one 5 and 3-amino-2-thioxo-2,3-dihydroquinazolin-4(1H)-one 6 were the most promising in this series towards the cancer cell lines and EGFR." (PMID 33357002, 2021). "The cancer cells have their own molecular interactions which expressing more receptors (p‐glycoprotein, enhance folate receptor and EGFR), biomarkers (α‐methylacyl coenzyme A racemase) and proteins (hepsin, Pim‐1, protease/KLK4)." (PMID 34694743, 2021). "Hepatocellular-carcinoma-related protein-1 (HCRP-1) is known to be downregulated in various malignant tumors, and its downregulation induces anoikis resistance via Bim downregulation in the EGFR–Akt pathway." (PMID 33440835, 2021). "Various therapeutics have been designed to target EGFR in cancer treatments, including antibody therapeutics such as cetuximab, and small-molecule tyrosine kinase inhibitors such as gefitinib and erlotinib." (PMID 34054523, 2021). "Epidermal growth factor receptor (EGFR), a membrane protein receptor, its mutations or amplification are the major driving factors of cancer, especially in NSCLC." (PMID 33777739, 2021). "In our study, we demonstrated that blue LED irradiation inhibited EGFR phosphorylation and prevented its activation, subsequently leading to depression of cancer cell growth." (PMID 33960631, 2021). "HER2 is a member of human epidermal growth factor receptor (HER/EGFR) tyrosine kinase family, which is frequently overexpressed in many cancer types." (PMID 34267653, 2021). "Compound 42, which displayed IC50 values ranging from 1.3–1.8 μM against the cancer cell lines and an IC50 value of 0.3 μM against EGFR in vitro, also caused increased expression of the apoptotic marker caspase-3 in PANC-1 cells." (PMID 34299488, 2021). "Despite an initial response, the efficacy of anti-EGFR therapies can be limited by the presence of acquired mechanism(s) of cancer cell resistance." (PMID 33920531, 2021).